ERBB3 (erb-b2 receptor tyrosine kinase 3)
Diseases named in the same sentence as ERBB3 in open-access papers (continued):
Sharing a sentence is not in itself a finding about the gene and the disease.
cancer (continued). "ErbB3 is a member of EGFR family of receptor tyrosine kinases, which serves as a homolog to EGFR (ErbB1) and HER2 (ErbB2) and plays an important role in cancers." (PMID 34400880, 2021). "We confirmed that iBET-151 reduced the expression of RTK mRNA and proteins, including EGFR, ERBB3, MET, and IGF-1R, thereby regulating cancer cell growth and survival." (PMID 33412753, 2020). "ERBB3 is an essential member of EGFR family with receptor tyrosine kinase activity and serves as an oncogene in cancer development and progression 30,31,44." (PMID 32206115, 2020). "All anti-cancer activities are given by activation or inhibition of pathways such as HDAC1/PTEN/Akt, EGFR/ErbB2/ErbB3, and PI3K/Akt; PI3K-AK-mTOR, HDAC1/PTEN/Akt; Wnt/β-catenin." (PMID 32923398, 2020). "Among these significant gene sets were several cell-signaling pathways, including the ERBB3 pathway, the PI3K/AKT signaling in cancer pathway and a pathway related to GRB7 events in ERBB2 signaling." (PMID 33154357, 2020). "ERBB2 and ERBB3 genes belong to the epidermal growth factor receptor (EGFR) family, and they had been identified as common driver genes of multiple cancer types by promoting solid tumor growth." (PMID 32038722, 2019). "miR-205 actively targets the 3'UTR of some key genes such as AR, BCL2, ERBB3, PTEN, and VEGF-A that play important roles in cancer cell invasion and metastasis." (PMID 31756185, 2019). "Molecular method was based on the analysis of selected genes expression related to hypoxia (HIF1A, ANGPTL4, TGFB1, VEGFA, ERBB3, CA9) or specific for inflammation in hypoxic sites (CCL2, CCL5) at various time points after CT26 cancer cells inoculation." (PMID 30412628, 2018). "We found that five genes were related to cancer, including BNIPL, ERBB3 and PRKG1, which were also been detected by degree or eigenvector measures." (PMID 29301256, 2018). "Given our preclinical and clinical data to date, anti-ErbB3 therapies like seribantumab may have the potential to significantly enhance clinical activity of standard of care therapies by combating persistent drug-tolerant cancer cells via the inhibition of the HRG-ErbB3 pathway." (PMID 28725482, 2017). "ErbB2, a member of the ErbB family of receptor tyrosine kinases, triggers numerous oncogenic signals in cancer cells by binding other members of the family, such as Epidermal Growth Factor Receptor (EGFR) or ErbB3." (PMID 29285258, 2017). "Interestingly, we also observed that ErbB3 was also rarely overexpressed in squamous lung cancer samples (unpublished observations), suggesting that ErbB3 signaling in cancers of squamous origin, which often express NRG1, may lead to downregulation of ErbB3 mRNA expression." (PMID 28723928, 2017). "Sensitivity analysis identified ErbB3 as the most critical activator of phosphoinositide 3-kinase (PI3K) and Akt signaling, a key pro-survival pathway in cancer cells." (PMID 28725482, 2017). "Together, these results support our initial finding that that EGFR, ERBB3 and CDKN1B expression predict differential dependence on PI3K/AKT and MAPK signaling in HER2+ cancer cells." (PMID 27035903, 2016). "Members of the human epidermal growth factor receptor (HER) family of receptor tyrosine kinases EGFR (HER1, ERBB1), HER2 (ERBB2), HER3 (ERBB3), and HER4 (ERBB4) are therapeutic targets in several cancers." (PMID 27610130, 2016). "In our study, expression of the SLC3A2-NRG1 fusion gene increased cancer cell proliferation in vitro and in vivo through ERBB2 and ERBB3 heterocomplexes." (PMID 27626312, 2016). "Three cancer cells (black color, Calu-3, HCC827, and HCC358) showed higher ERBB2 and ERBB3 levels than other cell lines and were selected for further studies." (PMID 27626312, 2016). "Furthermore, since PI3K integrates both the ErbB2/Grb2/SOS/RAS and ErbB3/p85 pathway, the ErbB2-overexpressing cancer cells become addicted to the PI3K signalling hub, as manifested by increased susceptibility to PI3K inhibitors, compared with ErbB3 inhibition." (PMID 27255951, 2016).
cancer (continued). "Our results suggest that human cancer patients with relatively high levels of EGFR, ErbB3, and HRG are the potential patient population of the anti-EGFR/ErbB3 DVD-Ig protein treatment." (PMID 25997020, 2015). "In accordance with the qRT-PCR data, ERBB3 was detected in LIM1215, LIM1899, CACO2 and SW480 cancer cells." (PMID 26367378, 2015). "Activation of the survival signaling - PI-3 K/Akt pathway by erbB3 (via interactions with another RTK, particularly erbB2) also gives rise to chemoresistance in cancer treatment." (PMID 24886126, 2014). "The erbB receptors, including the epidermal growth factor receptor (EGFR), erbB2 (also known as HER2/neu), erbB3 (or HER3), and erbB4 (or HER4), are often aberrantly activated in a wide variety of human cancers." (PMID 24886126, 2014). "In most MET-amplified cancers, MET signals are mediated through human epidermal growth factor receptor 3 (HER3/ErbB3)." (PMID 28548075, 2014). "ERBB3 limits the impact of exclusively targeting ERBB1/EGFR or ERBB2/HER2 and provides a route for acquired resistance to anti-cancer drugs that inhibit ErbBs." (PMID 25248370, 2014). "Recently, a new anti-erbB3 Ab (MP-RM-1) and its humanized version (named EV20) both have been shown to exhibit antitumor activity against various cancer types in vitro and in vivo." (PMID 24886126, 2014). "Our computer-based search for miR-205 targets also indicated that ErbB3 and VEGFA were cancer-related target genes of miR-205 in HuH28 cells." (PMID 24147037, 2013). "The epithelial growth factor receptor (EGFR) family consists of four members, EGFR (HER1), ErbB2 (HER2), ErbB3 (HER3), and ErbB4 (HER4), and has been shown to play an important role in metastasis and tumorigenesis in many types of human cancers." (PMID 22479527, 2012). "The EGF receptor family consists of four members: ErbB1/EGFR/HER1, ErbB2/HER2/Neu, ErbB3/HER-3 and ErbB4/HER-4 that are important for cancer development." (PMID 23173670, 2012). "ERBB3 is a critical activator of PI3K signaling in EGFR (ERBB1)-, ERBB2 (HER2)-, and MET-addicted cancers." (PMID 23691449, 2012). "The identification of many well-defined cancer gene markers (representing oncogenes), such as EGFR, osteopontin (SPP1), ERBB3, MALAT1, S100A2, S100A6, ABCC3 and ELN3, as highly discriminative genes by the ECD is quite encouraging." (PMID 22369099, 2011). "Thereafter, we and other investigators confirmed the inhibitory effects of EGCG on other RTKs including erbB3/Her3, erbB4/Her4, IGFR, PDGFR, FGFR, and VEGFR employing a variety of cancer cell lines derived from different organs." (PMID 21274257, 2011). "The ErbB tyrosine kinase superfamily, comprising the epidermal growth factor receptor (EGFR; also known as ErbB1/HER1), ErbB2 (HER2/neu), ErbB3 (HER3) and ErbB4 (HER4), plays important roles in cancer development and progression." (PMID 21789172, 2011). "EGCG inhibits the activation of EGFR (erbB1), HER2 (neu/erbB2) and also HER3 (neu/erbB3), which belong to subclass I of the RTK superfamily, in various types of human cancer cells." (PMID 19325845, 2008). "ErbB3, the major EGFR family member that activates the PI3K/Akt pathway, is required for ErbB2-induced cancer cell proliferation, transformation and colony formation in vitro." (PMID 18700973, 2008). "ERBB3 activating alterations were detected in 1.8% (n = 7,571) of tumors in the overall cohort and were most prevalent in small bowel (7.7%), bladder (6.1%), urinary tract (4.6%), uterine (4.3%), and GEC (4.1%) cancers." (PMID 40178042, 2025). "The stem cell cluster was identified as the cancer stem cells (CSCs) by upregulating the CSCs markers, such as CD55, ERBB3, KRT8, in the volcano plot based on the differentially expressed genes (DEGs, following the STOmicsDB platform default standards) of the stem cell." (PMID 40822927, 2025).
cancer (continued). "In particular, ERBB3 has been proposed to be the preferred dimerization partner for ERBB2, and to critically contribute to ERBB2-mediated transformation in breast and other cancer types." (PMID 38806620, 2024). "ERBB3/HER3 lacks or has little intrinsic tyrosine kinase enzymatic activity; however, it frequently forms heterodimers with other ERBB/HER tyrosine kinases and, in cancer cells, can activate oncogenic signaling." (PMID 38369520, 2024). "The therapeutic potential of ERBB3 inhibitors, such as AZD8931, demonstrates that TFE3-RCC cells lacking ARID2 are more sensitive to this treatment, providing promising directions for improving outcomes for patients with this aggressive cancer subtype." (PMID 39727945, 2024). "Approximately 0.15–0.5% of cancers harbor NRG1 fusions that upregulate NRG1 activity and hence that of the cognate ERBB3/ERBB4 (HER3/HER4) receptors; abrogating this activity with small molecule inhibitors/antibodies shows preliminary tissue-agnostic anti-cancer activity." (PMID 38369520, 2024). "Indeed, the EGFR and ERBB families (ERBB2, ERBB3 and ERBB4) were also ranked in the top 10 cancer driver targets in the transcriptional networking, suggesting their roles in uPAR-mediated tumorigenesis processes were highly anticipated." (PMID 37895906, 2023). "Indeed, four proteins (P08581|MET, P21860|ERBB3, P04626|ERBB2, and P25445|TNR6) from HCT116-specific group and one protein (P46531|NOTC1) from DKO1-specific group are oncogene products (cancer driver score = 4)." (PMID 36639722, 2023). "HER2 is part of the epidermal growth factor receptor (EGFR/Erb) family of tyrosine kinase receptors, which consists of four members-EGFR/HER1/ErbB1, HER2/ErbB2, HER3/ErbB3, and HER4/ErbB4-and is closely related to cell proliferation, differentiation, migration, and cancer development." (PMID 36937848, 2023). "On the contrary, decreased levels of neuregulin 1 (NRG1), a direct ligand of ERBB3 and ERBB4 tyrosine kinase receptors, which activate ERBB receptors, could be responsible for the inhibition of cancer cell growth." (PMID 37834191, 2023). "Likewise, zenocutuzumab, an ERBB2/ERBB3 (HER2/HER3) bispecific antibody, is under evaluation in clinical trials for patients with NRG1-positive fusions in cancer and has a 34% ORR." (PMID 37958963, 2023). "Therefore, some catalytically defective RPTKs involved in tumorigenesis, such as PTK7, Erb-B2 receptor tyrosine kinase 3 (ErbB3), and EPH receptor A10 (EphA10), are considered target molecules for cancer therapy." (PMID 36293051, 2022). "The overexpression and/or mutations of epidermal growth factor receptor (EGFR) family proteins, i.e., EGFR (HER1), ERBB2, ERBB3 and ERBB4, are often found in multiple types of cancer cells and are considered to be a significant prognostic indicator in the clinical intervention of cancer." (PMID 35163685, 2022). "Moreover, targeting ERBB3 and EGFR signaling is an effective method for overcoming cancer progression and resistance to anticancer therapy." (PMID 35681658, 2022). "This study shows a potential involvement of the ErbB2/ErbB3 pathway in CSC generation and could lead to new insight into the mechanism of tumorigenesis and the way of cancer prevention." (PMID 35177646, 2022). "For example, ERBB3 (HER3), one of the EGFR family proteins, can undergo NEDD4L-mediated ubiquitination and degradation to down-regulate the signal transduction pathways of occurrence and development in cancers." (PMID 37305161, 2021). "Elgemtumab (LJM716) binds domains 2 and 4, and locks ErbB3 in inactive conformation, thus inhibiting both ligand-dependent and ligand-independent proliferation of various cancer cell lines, without direct interference with heregulin binding." (PMID 34572289, 2021). "Similarly, the application of the R-package Survminer revealed the prognostic significance of CK19 at primary diagnosis as well as of other cancer-related (CDH5 and TERT) and EMT markers (FAM83A, PTHLH, and ERBB3) at disease progression." (PMID 34834576, 2021).
cancer (continued). "ErbB3/HER3 is a member of the epidermal growth factor receptor family of receptor tyrosine kinases, which play an important role in the development and progression of cancer." (PMID 34443781, 2021). "Cancer cells of different origin, when exposed to standard chemo- or target-therapy promptly react through the activation of a common survival pathway centred around the EGFR receptor family member ErbB3 and its downstream signalling elements PI3K and AKT." (PMID 31557826, 2019). "Therefore, cancer‐related RTK become preferable targets for ADC development, e.g. RON, PTK7, FLT3, FGFR2, FGFR3, ERBB3, KIT and EPHA2." (PMID 31116512, 2019). "The result was unexpected because numerous studies in HNSCC and other cancer cell lines generally indicated that co-targeting ErbB3 with EGFR or other pathways, chemotherapy, or radiotherapy, was required to yield a significant benefit from ErbB3 inhibition." (PMID 29305574, 2018). "In contrast, there has been relatively less emphasis on ERBB3 as a molecular target for therapy and no targeted therapies for ERBB3 have been approved for cancer treatment till to date." (PMID 29321816, 2017). "ErbB3/HER3 is a member of the epidermal growth factor receptor family of receptor tyrosine kinases comprising HER1 (EGFR), HER2 (ErbB2), HER3 (ErbB3) and HER4 (ErbB4) which play an important role in the development and progression of cancer." (PMID 28448604, 2017). "In addition, when present, the percentage of PCa expressing ErbB3 in the nucleus was higher in CRPC (median 10%, range 2–95%) than in HS cancers (median 2%, range 1–20%) (p = 0.007, Mann Whitney test)." (PMID 27191720, 2016). "First, we sought to determine whether protein expression of EGFR, ERBB3 and CDKN1B, could be used to predict differential sensitivity to anti-cancer drugs in HER2+ cancers." (PMID 27035903, 2016). "Due to the absence of an active intracellular tyrosine kinase domain, ERBB3 was disregarded for several years as a cancer target." (PMID 26367378, 2015). "The most intriguing feature of ERBB3 is that it contains multiple binding sites for the p85 regulatory subunit of PI3K, allowing it to activate the AKT pathway, a critical signal in a variety of cancers." (PMID 24970817, 2014). "Not surprisingly, the overexpression of ERBB3 has been frequently detected in many types of human cancers, and accumulating evidence strongly suggests that ERBB3 plays a crucial role in cancers driven by EGFR and ERBB2." (PMID 24970817, 2014). "Unlike the widely studied erbB2 and EGFR in human cancers, there has been relatively less emphasis on erbB3 as a molecular target for cancer treatment." (PMID 24215614, 2013). "Although a number of strategies targeting erbB2 are being used in the clinic, no erbB3-targeted therapy has been approved for cancer treatment." (PMID 24168763, 2013). "The expression of the proliferation-associated marker Ki-67 at a higher frequency in ErbB3-positive NSCLC cases than in ErbB3-negative tumors was suggestive of a contribution of ErbB3 to an aggressive cancer behaviour." (PMID 22889873, 2012). "In contrast, in prostate tissues, nuclear ERBB3 is reported only in cancer tissues and not in normal tissues, increasing with Gleason grade and disease recurrence." (PMID 21364580, 2011). "In 65% of patients (41 of 63), cancer tissues showed an overexpression of EGFR compared with normal tissues, whereas 79 and 81% (50 of 63 and 51 of 63, respectively) of patients showed an overexpression of cytoplasmic Her-2 and ErbB3, respectively." (PMID 20216540, 2010). "Erbb3, a member of the EGFR receptor tyrosine kinase family, binds to neuregulins (NRGs) and plays an important role in cellular processes during development and cancer progression." (PMID 18773073, 2008). "Overexpression of ERBB3 appears to result from increased levels of gene transcription since in none of the cell lines or primary cancers analysed did we find evidence of gene amplification." (PMID 1333787, 1992).
cancer (continued). "We could observe some pathogenic variants in different cancer-associated genes including BRAF, FGFR2 or ERBB3 that, although not currently available in the clinical practice, may be considered for treatment in future clinical trials." (PMID 39003322, 2024). "Considering that the ERBB family member ERBB3 was reported to recruit PI3Kβ and thereby drive PI3Kα inhibitor resistance in HER2‐amplified and PIK3CA mutant cancers, we hypothesized that ALK inhibition may similarly activate EGFR and thereby regulate PI3Kβ function." (PMID 36423211, 2023). "As the TCGA dataset lacks expression data from normal ovarian tissues, we could not compare ERBB2 and ERBB3 expression between cancer and normal ovarian tissues." (PMID 35740327, 2022). "Interestingly, in non-basal and TKI resistant cancer cells (J82), inhibition of EGFR phosphorylation mediated by erlotinib was associated with increased mRNA expression of EGFR (FC: 44.6), ERBB3 (FC: 92.3) and EREG (FC: 3.5)." (PMID 32978523, 2020). "Yet, overexpression of ERBB3 and activation of ERBB3 signaling has been observed in different types of human cancers, including NSCLC, in which these events have been related to drug resistance (including TKI-resistance), cancer progression and poor patient survival." (PMID 31266248, 2019). "This is consistent with previous findings indicating that overexpression of ErbB3 may not be sufficient to promote cancer cell proliferation and survival in isolation, but requires activation by HRG." (PMID 31728045, 2019). "The central hypothesis underlying seribantumab development is that ligand-driven signaling through ErbB3 serves as a widespread cancer cell survival pathway, rendering cancer cells tolerant to standard of care therapy, regardless of the class of therapy." (PMID 28725482, 2017). "In addition to a global view on ERBB3/ERBB4 signaling, our data create potential opportunities for follow-up studies to promote a better mechanistic understanding and explore potential links to cancer biology." (PMID 26745281, 2016). "To date, no erbB3-targeted therapy has been approved for cancer treatment." (PMID 24886126, 2014). "Notably, Trop2 loss triggers sensitivity to anti-ErbB3 antibodies, which results in reduced proliferation and tumorigenic growth of Trop2 negative HNSCC cancer cells." (PMID 25238142, 2014). "ErbB3 and pErbB3 were nearly absent in glandular epithelial cells of colorectal mucosa adjoining cancer tissue.ErbB4 and pErbB4 immunoreactivity was observed in cancer cells in 33 (21%) and 25 (16%) cases, respectively." (PMID 25416285, 2014). "(ErbB3: cancer tissues 3264±1032 vs. normal colorectal tissues 1038±354, P = 0.0074, ErbB2: cancer tissues 2616±2019 vs. normal colorectal tissues 338±154, P = 0.016, c-MET: cancer tissues 3812±739 vs. normal colorectal tissues 978±313, P = 0.0057 by Mann-Whitney U test)." (PMID 24205104, 2013). "Thus, the expression of ERBB2, ERBB3 and ERBB4 in EGFR driven cancer may be important to predict the outcome of TKI treatment." (PMID 23758840, 2013). "Currently, no erbB3-targeted therapy has been approved for cancer treatment." (PMID 24168763, 2013). "The evidence that a subset of cancer cell lines show simultaneous production of NRG and IGF1 and this gives rise to simultaneous activation of both receptors led Merrimack to generate a bispecific antibody directed against ErBB3 and IGF1R which was called MM-141." (PMID 22889873, 2012). "Recent evidence from both basic and clinical studies suggests that ERBB3 (HER3) serves as a key activator of downstream signaling through dimerization with other ERBB proteins and plays a critical role in the widespread clinical resistance to EGFR and HER2 targeting cancer therapies." (PMID 23342251, 2012). "Indeed, treatment of EGFR-positive cancer cells with CL4 strongly inhibits both the EGF-induced tyrosine phosphorylation of EGFR and ErbB2 and the Hrg-dependent tyrosine phosphorylation of EGFR and ErbB3." (PMID 21915281, 2011).